CD4 (CD4 molecule)
Diseases named in the same sentence as CD4 in open-access papers (continued):
Sharing a sentence is not in itself a finding about the gene and the disease.
tumor (continued). "In six of nine tumor types examined, loss of GATA4 was significantly associated with decreased abundance of specific immune-related transcript sets indicative of tumor-infiltrating cytotoxic CD8 T cells, CD4 T cells, and B cells." (PMID 35017504, 2022). "In support of this hypothesis, cancer patients given anti-CTLA-4 and anti-PD-1 therapy develop tumor-specific cytolytic CD4 T cells marked by enhanced Eomes expression." (PMID 36358898, 2022). "Similarly, the reduction of tumor immune infiltrates with PRC2 loss was seen across all major subclasses of immune cells, including MHC-II+CD11c+ DCs, TCRβ+ T cells (both CD4+ and CD8+), F4/80hiCD11b+ macrophages, and to a lesser extent B220+ B cells." (PMID 35852856, 2022). "Following OV-induced necrosis and pyroptosis of virus-infected tumor cells, tumor antigens attract Batf3 + DCs and scavenging macrophages, resulting in enhanced antigen presentation and subsequent stimulation of specific CD8+ and CD4+ T lymphocytes against the tumor antigen." (PMID 35488303, 2022). "Virus-reactive TCR clonotypes could also be recovered from the tumor (primary tumor n=1, metastasis n=5 or both sites n=1) and from the blood directly ex vivo (n=6, all CD4, some of which were also observed in the primary tumor (n=1) or metastasis (n=2))." (PMID 35361728, 2022). "Furthermore, it induced a significant increase in the proportion of tumor-infiltrating CD4+ and CD8+ T cells." (PMID 36352411, 2022). "Finally, we evaluated the possible immune-regulatory function of PD-L2 on CD68+ macrophages and CD4+Foxp3+ Treg cells in the tumor microenvironment in NPC." (PMID 36606190, 2022). "We observed that the CD4/CD8 ratio was higher in the ER+ miR-18a high tumor specimens (p < 0.0001)." (PMID 35626709, 2022). "Moreover, CD4+ T cells can cooperate with cytotoxic T lymphocytes in bystander killing of cancer cells and can also acquire cytotoxic function so as to kill tumor cells expressing MHC-II as effectively as CD8+ T cells." (PMID 36385379, 2022). "The uptake of sialylated antigens by DCs was shown to enhance the induction of Tregs through engagement of Siglec-E, which might reflect the interactions between DCs and naïve CD4+ T cells in the hypersialylated tumor microenvironment." (PMID 36322632, 2022). "In their trial, Adriamycin selectively promoted the apoptosis of MDSCs in the spleen, blood, and tumor bed; inhibited the immunosuppressive activity of residual MDSCs; and increased the proportion of CD4+ T cells, CD8+ T cells, NK cells, and their downstream effector factors." (PMID 35892835, 2022). "However, unlike CD4 + conventional CAR-T cells, CD8 + conventional CAR-T cells showed lower expression level of CD98 when co-cultured with tumor cells, revealing amino acid metabolism mostly active in CD4 + T cells." (PMID 35869100, 2022). "CD4+PD-1+ T cells were predominantly detectable in tumor tissues of CRC patients, which may lead to T-cell exhaustion and cancer progression." (PMID 35655158, 2022). "CD8+ and CD4+ T cell numbers in tumors increased dramatically in combination treatment group while shown a decrease of Treg cells (Foxp3+) when compared with other groups in the tumor." (PMID 36329529, 2022). "Because CD4IL2RALO cells significantly block cytotoxic CD4+ T cells from killing tumor cells, the strong inhibition of CD4IL2RALO Tregs by Mito‐ATO could contribute to the observed increased proportion of activated cytotoxic CD 4+ T cells in TIME." (PMID 35243806, 2022). "To verify if tumor‐infiltrating T cells were responsible for Smad4 loss‐induced tumor suppression, we depleted T cells via intraperitoneal injection of anti‐CD8 or anti‐CD4 neutralizing antibodies prior to tumor cell inoculation." (PMID 35064757, 2022). "Interestingly, depletion of CD4+ or CD8+ T cells partially but significantly inhibited the tumor invasion observed in Apc/Dok3 mice." (PMID 36970719, 2022).
tumor (continued). "Comparing with the control groups, treatment with URB + US not only increased the number of functional CD4+ T cells in tumor, including IFN-γ+CD4+ and TNF-α+CD4+ T cells, but also elevated the number of functional CD8+ T cells, such as IFN-γ+CD8+, TNF-α+CD8+ and GranzymeB+CD8+ T cells." (PMID 35918309, 2022). "PD-L1 expressed by glioma, in addition to increasing the number of T-reg cells, inhibits the functions of T lymphocytes and induces apoptosis of tumor-specific CD4+ and CD8+ T lymphocytes by decreasing the production of cytokines such as Inter-leukin-2 (IL-2) and interleukin-10 (IL-10)." (PMID 36555334, 2022). "Additionally, we identified 4 distinct T lymphocytes subsets, of which cytotoxic CD8+ T cells predominated as effectors in tumor tissues, whereas tumor infiltrating FOXP3+ CD4+ regulatory T cells exhibited highly immunosuppressive characteristics." (PMID 35219893, 2022). "CD4+ T cells have long been recognized as an important component of tumor immunotherapy, as they are capable of promoting or suppressing anti-tumor cytotoxic CD8+ T cell responses in secondary lymphoid organs or tumors, hence modulating the tumor immune microenvironment." (PMID 35892841, 2022). "CD4+ Tregs have immunosuppressive functions and are therefore tumor-promoting." (PMID 35326515, 2022). "This upregulation of CXCR3 on CD8+ T cells enhanced their migration toward the IFNγ-inducible ligands CXCL9, -10, and -11 to stimulate trafficking into the tumor, and presumably also increased trafficking of CD4+ T and NK cells, which are also regulated by this mechanism." (PMID 36382146, 2022). "However, the fact that MCC results from MCPyV oncoproteins in 80% of cases has facilitated the study of the role of tumor-specific CD4+ T-cell help in MCC antitumor activity." (PMID 36551547, 2022). "The application of anti‐OX40 could promote tumor‐infiltrated CD4+ T‐cell proliferation and reduce tumor metastasis, which provides a therapeutic target for tumors." (PMID 35474948, 2022). "Tumor-infiltrating exhausted PD-1hiCD39+ tumor-antigen (Ag)-specific CD4 T cells contribute to the response to immune checkpoint blockade (ICB), but their circulating counterparts, which could represent accessible biomarkers, have not been assessed." (PMID 35954341, 2022). "Therefore, to identify lymphocyte populations essential for tumor invasion in Apc/Dok3 mice, we crossed Apc/Dok3 mice with CD4 and/or CD8-deficient mice to deplete CD4+ and/or CD8+ T cells." (PMID 36970719, 2022). "Also, cotreatment inspired the population of antigen-presenting cells (APCs), CD8+ and CD4+ T lymphocyte cells in tumor tissue, thereby eliciting robust antitumor responses in treated mice against tumor tissue." (PMID 35508982, 2022). "It is important to remain cautious when interpreting results from ACT studies and extending them to immunocompetent tumor-bearing hosts, as the adoptively transferred CD4+ T cells in these studies were observed to mediate their antitumor effects under lymphopenic conditions." (PMID 36159781, 2022). "Similarly, examining all T cells, tumor only treated mice had an increase in activated CD8 T cells and CD4 T cells in the flank tumor TME." (PMID 36385142, 2022). "Furthermore, transfer of sfRON knockout CD4+ T-cells to RON WT mice was largely protective against metastatic outgrowth following tumor cell injections." (PMID 35454943, 2022). "As reported in prior studies, high MMP1 expression may promote the production of tumor-killing immune cells (aDC, NK CD56bright cells, macrophages, Th1/2, TFH, T helper cells and CD4+ T cells) and cause regional inflammation and fibrosis (monocyte and CAF)." (PMID 35948625, 2022). "We found that the mRNA expression of C1QA, C1QB, C1QC, C5AR1, C3AR1, C1QR (CD93), CR1, CR2, CR3 (ITGAM), and CR4 (ITGAX) were positively associated with almost all kinds of tumor immune cells, including CD8+ T cells, CD4+ T cells, B cells, macrophages, monocytes and DCs." (PMID 34813686, 2022).
tumor (continued). "Besides, BRAF inhibition was associated with increased infiltration of CD4+T, CD8+T cells and reduced levels of myeloid-derived suppressor cells (MDSCs), tumor-associated macrophages (TAMs)." (PMID 36531226, 2022). "Therefore, we suggest that understanding the education of tissue resident macrophages/DC by effector CD4 T cells is not only relevant for tumor immunotherapy but also for other tissues undergoing immune responses, and, perhaps, for tissue homeostasis." (PMID 35903540, 2022). "One of the most systematic evaluations performed single‐cell RNA sequencing (scRNAseq) of seven ESCCs and identified that some ESCCs actually have high numbers of tumor‐infiltrating T cells but that the majority of the proliferating immune cells are exhausted CD4/8 T cells and NK cells." (PMID 35035956, 2022). "However, the reinfusion of CD4+ T cell products was demonstrated to result in a partly impressive tumor regression, which pointed to the therapeutic potential of CD4+ T cells." (PMID 36077730, 2022). "On the other hand, T CD4+ cells infiltrate into the tumor region and exert anti-cancer activity." (PMID 37305016, 2022). "Tumor-evoked regulatory B cells (tBregs), which are phenotypically similar to activated but less proliferative mature B2 cells, reportedly promote breast cancer metastasis by converting quiescent CD4+ T cells into Tregs." (PMID 36158661, 2022). "HLA class I molecules are essential for presenting tumor antigens to naïve T cells, whereas HLA class II molecules stimulate the conversion of these naïve T cells into activated T cells by delivering exogenous antigen peptides to CD4 + T cells." (PMID 36543836, 2022). "We analyzed tumor infiltrating CD45+ hematopoietic cells including CD4+ and CD8+ T cells." (PMID 35514996, 2022). "In addition to the level of tumor infiltrating CD4+ and CD8+ T cells, we also evaluated B cell, NKT cell and NK cells infiltration after HER2-DC1 i.t. and anti-HER2 antibodies combination treatment." (PMID 35710296, 2022). "Th2 cells (CD4+/GATA3+ cells) were also represented in the tumour areas, ranging from 10% to 25%." (PMID 33948980, 2022). "LncRNA MAIT is mainly expressed in CD4+ T cells from HCC tumor tissues and paracancerous tissues." (PMID 36300115, 2022). "Taken together, these observations underscore the dual function of type 1 T helper (TH1) CD4+ cells in shaping both vascular and immune tumor compartments, strongly suggesting their determinant role in the outcome of immune checkpoint and angiogenetic targeting." (PMID 35805021, 2022). "Interestingly, the combination group had the highest percentages of PD-1+ tumor CD4 and CD8 T cells." (PMID 36300124, 2022). "While professional antigen presenting cells expressing MHC-II are found in the tumor microenvironment and stimulate CD4+ T cell costimulatory pathways, the intrinsic expression of MHC-II in tumor cells is increasingly recognized as a key pathway in anti-tumor immune responses." (PMID 35992816, 2022). "Finally, high-dose radiation in combination with a TLR9 agonist in pre-clinical tumor models enhanced anti-tumor immune responses via increasing activated CD4+ and CD8+ T cells within the tumor microenvironment." (PMID 35055015, 2022). "Furthermore, CD4+ memory T cells constitute a vital component of the TME that affects tumor occurrence and progression." (PMID 35589807, 2022). "cDC2s played an antitumor role by presenting tumor-derived antigen to CD4+ conventional T cells." (PMID 35571564, 2022). "Whether TLS B cells or DCs cross‐present tumour antigens to CD8+ T cells or whether CD4+ Th cells are involved in the generation of CD8+ cytotoxic T cell responses inside or outside TLSs have not been settled." (PMID 36245289, 2022). "Indeed, glycans coupled to antigens can efficiently target DCs through DC-SIGN, leading to antigen internalization, cross-presentation and subsequent elicitation of tumor-specific CD4+ and CD8+ T-cell responses." (PMID 36353633, 2022).
tumor (continued). "Lastly, we examined whether CD14CTX and CD4SOCS3 interact within the tumor microenvironment since we could also identify a population of SOCS3+CD4+ T cells in biliary tumors by scRNAseq." (PMID 36130508, 2022). "Interestingly, we observed a significant macrophage and Treg infiltration in the EMTrLS-high group, accompanied by an increased infiltration of immune cells with tumor-killing effects, such as CD4 T cells and CD8 T cells." (PMID 36090045, 2022). "Interestingly, a significant correlation was observed in tumor tissues between levels of FoxP3+ Tregs and CD4+PD-1+ T cells (r = 0.548, p = 0.008)." (PMID 35455287, 2022). "CD4+ T cells are divided into anti-tumor and pro-inflammatory T helper type 1 (Th1) cells, immunosuppression Th2 cells, Th17 cells and Tregs, which secretes immunosuppressive cytokines such as IL-10 and transforming growth factor β (TGF-β), regulating the functions of T cells." (PMID 37305350, 2022). "Despite this decrease, the observed durable tumor control led us to hypothesize that this activated CD4+ and CD8+ Teff cell population was more rapidly renewed compared with the Treg population, resulting in a beneficial Teff/Treg ratio." (PMID 35955841, 2022). "In addition, CCL5 can mediate the recruitment and chemotaxis of Tregs, macrophages, DCs and MDSCs, as well as induce the Th2 polarization of CD4+ T cells, which consequently promote tumor growth and metastasis." (PMID 35327361, 2022). "In addition, the enrichment of CAF-S1 was correlated positively with PD-1+ and CTLA-4+ CD4+ T cell content but negatively with CD8+ T cells infiltration in tumor." (PMID 36324128, 2022). "In addition, combination therapy significantly decreased the proliferation of CD4+T cells and Tregs in the tumor." (PMID 35548349, 2022). "In the present study, we show that the presentation of MSLN-derived HLA class II-restricted peptides in the immunopeptidome is associated with longer patient survival, providing important insights into the role of immunopeptidome-guided CD4+ T-cell responses for tumor immune surveillance in OvCa." (PMID 35565389, 2022). "Tumor cell recognition by CD4+ T cells is also fundamental to tumor cell elimination by direct release of the proinflammatory cytokines interferon (IFN)-γ and tumor necrosis factor (TNF)-α, and by modulating the activity of other immune cells including CD8+ CAR T cells." (PMID 36591284, 2022). "Interestingly, CD4+ T cell depletion resulted in reduced tumor growth in both Asm-WT and Asm-KO mice." (PMID 36426850, 2022). "It is well known that MHC-II expression on tumor cells facilitates the recruitment of CD4+ T cells." (PMID 36009442, 2022). "Furthermore, CD4+ T-cells have a direct cytolytic effect on tumor cells, such as Fas-mediated cytolysis or tumor necrosis factor-related apoptosis-inducing ligand-induced apoptosis." (PMID 35804863, 2022). "Moreover, CD8+ and CD4+ T cells have been generally recognized as important anti-tumor immune cell subgroups with their cancer-cell killing efficacy, working as a crucial autoimmune gateway against cancer intrusion of an organism." (PMID 35345444, 2022). "Furthermore, the anti-tumor immune cell populations such as CD4+ activated memory T cells, CD8+ T cells, follicular helper T cells, memory B cells, M1 macrophages, and NK cells were more abundant in the C2 and C3 clusters." (PMID 35528236, 2022). "In this study, we investigated the gene expression pattern associated with tumor-infiltrating non-regulatory CD4+ and CD8+ T cells of HCC." (PMID 35092558, 2022). "Thus, MB49 TAMs can present tumor antigens in situ to effector CD4 TILs, triggering mainly an IFNγ response." (PMID 35903540, 2022). "Activation of TLR8 in cancer cells is found to prevent the induction of senescence in responder T cells and DCs, stimulate glucose uptake and glycolysis in CD4+ T cells, and induce apoptosis of MDSCs to enhance the anti-tumor effects of adaptive immune response." (PMID 35413927, 2022).
tumor (continued). "To determine if citrullinated GRP78 could be a target for CD4 T cells in tumour therapy we sought to identify citrulline specific responses restricted through two other HLA alleles." (PMID 36544781, 2022). "In the HPV18 tumor-bearing mice, the CD4+ lymphocyte ratio and the CD4+/CD8+ ratio of the vaccine group were significantly decreased, while the CD8+ lymphocyte ratio was significantly increased compared with those of the PBS blank control group and the AD-NC group (P < 0.05)." (PMID 35197089, 2022). "Furthermore, we found that NCAPG2 was significantly correlated with the level of B cells, CD8+ T cells, CD4+ T cells, macrophages, neutrophils and dendritic cells, and was negatively correlated with tumor purity." (PMID 35898895, 2022). "Changes in the tumour infiltrating immunophenotype were clear in tumours responding to αPD1 or combined αPD1 + metformin with the greatest changes associated with CD8+ TEM cells and CD4+ TEM cells." (PMID 36361684, 2022). "Collectively, these data imply that FDX1 expression is positively associated with the CD4+ T cell population and that T cell immune responses may be implicated in FDX1-mediated ccRCC tumor suppression." (PMID 36611966, 2022). "However, DCs loaded with total tumor RNA led to an increase in the frequency of activated CTLs and CD4+ T cells compared to DC-tumor hybrids." (PMID 35619702, 2022). "Previous studies indicated that CD4+ T lymphocytes could inhibit hepatocarcinogenesis and mediate tumor regression." (PMID 36700197, 2022). "Moreover, in a preclinical in vivo model of SCLC, the tumor impairment observed with the combined use of PARPi and anti-PD-L1 was accompanied by reduced CD4+FOXP3 Treg frequency and amplified cytotoxic CD8+ T cell response." (PMID 36428727, 2022). "Many scRNA-seq studies have found a link between significant infiltration of CD8+ T cells, CD4+ T helper 1 (Th1), regulatory T (Treg) cells, tumor-infiltrating exhausted T cells, CD45+ macrophages, dendritic cells, and myeloid cells, and a favourable outcome in mCRC." (PMID 36032085, 2022). "Furthermore, in addition to macrophages, almost all types of immune cells, including B cells, CD8+ T cells, CD4+ T cells, NK cells, and dendritic cells (DC), are present in the tumor microenvironment, and some are involved in the development of cancer." (PMID 35791393, 2022). "Moreover, CD98hc was also implicated as regulator of CD4 + T cells and IFN-γproduction, both of which play a role in anti-tumor immunity." (PMID 35193580, 2022). "In consequence, the promotion of tumor specific TH1 CD4 activation might be an attractive therapeutic option to enhance anti–programmed cell death protein-1 and its ligand (anti–PD-1/L1) efficacy." (PMID 35928870, 2022). "This may gradually build a tumor-specific Treg repertoire composed of metabolically adapted tTregs and pTregs, while CD4+ effector T cell repertoire may reflect a constantly replenished pool from periphery." (PMID 36248808, 2022). "Human MHC class II molecules (HLA-DMB, HLA-DMA, HLA-DRA, HLA-DOA) in the top 30 DMRs, which could attract inflammatory tumour-specific CD4+ T cells and dampen CD8+ T cell antitumour reactivity, were found to be hypomethylated in all CLL patients in our study." (PMID 36712882, 2022). "Our data show a much clearer dependence on CD8+ T cells for tumor regression than CD4+ T cells." (PMID 36073543, 2022). "In the memory stage, the CD8(+) and CD4(+) T cells work together with the tumor cells." (PMID 35522104, 2022). "There is accumulating evidence suggesting that CD4+ regulatory T cells (Tregs), which play a crucial role in inhibiting anti-tumour immunity, may be contributing to the clinical failure of ICIs." (PMID 35714487, 2022). "The number of CD8+ cytotoxic T cells and CD4+ Th cells increases with tumor malignancy." (PMID 35928818, 2022).